IL10 (interleukin 10)
Diseases named in the same sentence as IL10 in open-access papers (continued):
Sharing a sentence is not in itself a finding about the gene and the disease.
knee osteoarthritis (10 papers, 2010 to 2024). "We conclude that serum IL-10 concentrations are compromised in subjects predisposed to developing knee osteoarthritis following ligamentous trauma and in subjects with radiographic evidence of severe knee osteoarthritis." (PMID 33469085, 2021). "Serum IL-10 and the serum IL-10/TNF-α ratio were significantly lower while serum TNF-α was not significantly perturbed with severe compared to moderate knee osteoarthritis (i.e., Kellgren-Lawrence grade 4 vs. 3, respectively)." (PMID 33469085, 2021). "Differentiating moderate from severe knee osteoarthritis, however, revealed a lower serum IL-10 concentration and serum IL-10/TNF-α ratio with severe knee osteoarthritis." (PMID 33469085, 2021). "Additionally, higher ratios of IL-10/TNF-γ, IL-10/IL-12, and IL-10/IL-6 confirmed the predominance of anti-inflammatory over proinflammatory mediators in the serum of gonarthrosis patients with DM." (PMID 36141752, 2022). "The purpose of this investigation was to identify if serum IL-10 and TNF-α concentrations and their ratio (i.e., IL-10/TNF-α) are altered in subjects predisposed to developing knee osteoarthritis following ligamentous trauma and in those with severe knee osteoarthritis." (PMID 33469085, 2021). "Also, plasma levels of the anti-inflammatory cytokines IL-4, IL-7, IL-10, and IL-13 seem to increase after exercise in healthy subjects and IL-10 also in patients with knee-osteoarthritis." (PMID 28243900, 2017). "Based on these findings, we conclude that serum IL-10 concentrations are compromised without significant serum TNF-α deviations in subjects predisposed to developing knee osteoarthritis following ligamentous trauma and in subjects with severe radiographic evidence of knee joint space narrowing." (PMID 33469085, 2021). "PRP treatment for knee osteoarthritis effectively lowers the concentrations of inflammatory factors IL-6, IL-1β, TNF α, IL-17A, and IL-10, significantly alleviating knee joint pain and enhancing joint functionality." (PMID 37869166, 2023). "Lower proinflammatory cytokines in gonarthrosis patients with DM were accompanied by higher ratios of IL-10/TNF-γ, IL-10/IL-12, and IL-10/IL-6, underpinning the predominance of anti-inflammatory over proinflammatory mediators." (PMID 36141752, 2022). "Future research assessing the clinical utility of the serum IL-10/TNF-α ratio and other cytokine and cytokine ratios as systemic biomarkers capable of phenotypically differentiating the severity in knee osteoarthritis is warranted." (PMID 33469085, 2021). "However, in a study of patients with knee osteoarthritis, a reduction in pro-inflammatory molecules (MMP-2, IL-1B, IL-6, and IL-8) and an increase in anti-inflammatory molecules (IGF-1 and IL-10) were found at the 1-year follow-up after an SVF injection." (PMID 38391657, 2024). "Studies show that an increase in IL-10 may be transient, whereas TNF-α may be elevated chronically, and there is a possible role of low IL-10 to TNF-α ratio, contributing to severe knee osteoarthritis." (PMID 37371414, 2023). "Specifically, serum IL-10 and TNF-α concentrations and the serum IL-10/TNF-α ratio are compared between moderate (KL = 3, ≤ 50% joint space narrowing) and severe (KL = 4, > 50% joint space narrowing) knee osteoarthritis." (PMID 33469085, 2021). "IL-10/TNF-α (p = 0.001), IL-10/IL-6 (p = 0.001), and IL-10/IL-12 (p = 0.001) were significantly higher, while IL-10/IL-17 (p = 0.001) ratio was significantly lower in gonarthrosis patients with DM compared to gonarthrosis patients without DM." (PMID 36141752, 2022). "We hypothesized that serum IL-10 and TNF-α concentrations are higher following an anterior cruciate ligament injury and that the serum IL-10/TNF-α concentration ratio is lower with severe knee osteoarthritis." (PMID 33469085, 2021).
knee osteoarthritis (continued). "Results from this analysis indicate that serum IL-10 concentrations and the serum IL-10/TNF-α ratio are lower with severe knee osteoarthritis while the serum TNF-α concentration is not significantly different between disease severity subgroups." (PMID 33469085, 2021). "Serum IL-10 concentrations and the serum IL-10/TNF-α ratio were lower and serum TNF-α was not significantly different with a KL grade of 4 compared to a grade 3, implying a compromise in the circulating anti-inflammatory status with severe knee osteoarthritis." (PMID 33469085, 2021).
memory impairment (10 papers, 2012 to 2025). "Three studies measured IL-4 and IL-10, and only one reported an increase in IL-10 (together with other cytokines) that was associated with memory impairment." (PMID 41155372, 2025). "Chakrabarty also reported that adeno-associated virus-mediated expression of IL-10 causes Aβ accumulation and memory impairment in APP mice." (PMID 31592103, 2019). "In the present study, short-term aversive memory impairment was associated with increased levels of pro-inflammatory cytokines and decrease of regulatory mediators, such as IL-2 and IL-10, in the hippocampus and frontal cortex of P. berghei-infected mice." (PMID 24180288, 2013). "Males: ↑ monokine expression (IFN-γ, TNF-α, IL-10 and IL-13) and memory impairment compared to females." (PMID 39126053, 2024). "The Aβ1–42 injection also suppressed the M2 stage of microglia by decreasing the expression of the anti-inflammatory cytokine IL-10, which led to memory impairment." (PMID 36289849, 2022). "In another study, hesperidin decreased il-10 expression and reversed memory impairment in rat pups with hyperthermia-induced febrile seizures." (PMID 33505312, 2020). "In this work, LPS has been found to be a contributing factor in learning and memory impairments; a finding associated with an increase in the amount of IL-6 and TNF-α, but a drop in IL-10 of the hippocampus." (PMID 31579451, 2019). "In the present study, we demonstrated that BEZ reversed memory impairment and levels of hippocampal IL-10 in 10-months-old T41 mice." (PMID 31798451, 2019). "Similarly, our findings indicated that MISO significantly increased the levels of pro‐inflammatory factors (IL‐6, IL‐1β, and TNF‐α) and decreased that of the anti‐inflammatory factor IL‐10 in the hippocampus of offspring mice, which contributed to the observed spatial learning and memory impairment." (PMID 38945806, 2024). "Thus, although its mechanisms are not clear, BEZ protects against memory impairment, reduces microglial activation and reestablishes IL-10 levels, revealing beneficial effects, which should be further investigated for the treatment of AD." (PMID 31798451, 2019).
neurosyphilis (10 papers, 2017 to 2026). Infection of the brain or spinal cord by Treponema pallidum. "Further genetic regulation studies have identified polymorphisms in the IL-10 promoter region associated with the risk of neurosyphilis, particularly the GG genotype at the rs1800896 locus, which correlates with higher IL-10 secretion." (PMID 41602984, 2026). "Interleukin-10 in CSF was also regarded as a biomarker of neurosyphilis, especially of asymptomatic neurosyphilis." (PMID 36203756, 2022). "In another study, researchers detected changes in IL-1β, IL-4, IL-6, IL-10, IL-17A and IL-21 levels in the CSF of neurosyphilis patients before penicillin treatment." (PMID 36452956, 2022). "It is suggested that the CSF IL-10 concentration is useful for the diagnosis of neurosyphilis, especially for asymptomatic neurosyphilis patients." (PMID 36452956, 2022). "Recent studies showed a significantly elevated levels of IL-8, CC chemokine ligand 20 (CCL-20) in serum, elevated levels of CXCL13, interferon(IFN)-γ in CSF, and elevated levels of IL-6, IL-10, IL-17 in both serum and CSF of neurosyphilis patients." (PMID 36203756, 2022). "The sensitivity/specificity of CSF IL-10 in neurosyphilis and asymptomatic neurosyphilis were 86.7/91.7% and 83.3/91.7%, respectively." (PMID 36452956, 2022). "Similarly, in neurosyphilis, cerebrospinal fluid IL-10 has been identified as a potential biomarker in both symptomatic and asymptomatic patients, and is thought to facilitate bacterial persistence." (PMID 40529360, 2025). "Elevated concentrations of CXCL8, CXCL10, and IL-10 may also be potential biological markers of neurosyphilis, especially asymptomatic neurosyphilis." (PMID 38105236, 2023). "Therefore, inhibitory actions or production of the key anti-inflammatory cytokine IL-10 may be a potential treatment strategy for neurosyphilis patients with abnormal immunity." (PMID 33083463, 2020). "Some cases illustrated that levels of CSF IL-10 and CXCL-13 in patients with neurosyphilis elevated significantly." (PMID 33628742, 2020). "Furthermore, it was found that the CSF IL-10 level was positively correlated with the level of neuronal damage markers, the CSF protein concentration, the CSF white blood cell count and the CSF-RPR titer in neurosyphilis patients." (PMID 36452956, 2022). "In addition, studies have shown that the levels of CSF protein and white blood cell count are positively correlated with the inflammatory markers CXCL13, IL-6, and IL-10, which suggests that patients with atypical neurosyphilis may not have a significant or active inflammatory response." (PMID 41376790, 2025).
nonalcoholic steatohepatitis (10 papers, 2017 to 2025). "Using flow cytometry, we evaluated the plasma levels of IL-1β, IL-6, IL-12, TNF and IL-10 and their association with clinical and biochemical parameters of liver function during simple steatosis (NAFL) and nonalcoholic steatohepatitis (NASH) in biopsy-proven patients." (PMID 34447378, 2021). "It is also known that IL-10 exhibits therapeutic effects in various fibrotic diseases, including IPF and nonalcoholic steatohepatitis, by inhibiting the pro-fibrotic signaling pathway." (PMID 39052574, 2024). "In a murine model of non-alcoholic steatohepatitis, INT-767 significantly reduced pro-inflammatory cytokines production by macrophages such as IL-6 and TNF-a while increasing the anti-inflammatory cytokine IL-10." (PMID 37834329, 2023). "A previous study from our group indicated that BX795, a TBK1 inhibitor, suppressed the expression of inflammatory cytokines, such as IL-6 and IL-10, in a nonalcoholic steatohepatitis mouse model; however, the relevant mechanism was not defined." (PMID 34858401, 2021).
prion disease (10 papers, 2014 to 2024). A transmissible disease that is caused by a protein that is able to induce abnormal folding of normal cellular proteins, leading to characteristic spongiform brain changes, which are associated with neuronal loss without an inflammatory response. "For example, the onset of neuroinflammation and progression of prion disease was accelerated in mice deficient in IL-10." (PMID 24886300, 2014). "Furthermore, interleukin-10 knockout mice are more susceptible to prion diseases, post intraperitoneal or intracerebral inoculation with prion pathogens." (PMID 35216001, 2022). "Nevertheless, it has been reported that the anti-inflammatory cytokine IL-10 is neuroprotective concerning prion disease and traumatic brain injury, respectively." (PMID 39493812, 2024). "In contrast, the pathogenic state of prion diseases inhibits the development of Treg cells via the downregulation of TGF-β, IL-10, and PD-L1, clearly correlating the involvement of PrPC in Treg cell development." (PMID 33671884, 2021). "Among these cytokines, the only one playing a protective role in prion diseases is IL-10, as suggested by the finding that prion-inoculated IL-10 KO mice have a faster onset and progression of the disease." (PMID 33092220, 2020). "The role of anti-inflammatory cytokines in prion diseases mainly has been investigated by means of IL-4, IL-10, and IL-13 KO mice." (PMID 33092220, 2020). "Mice lacking IL-10 are susceptible to the development of prion disease and show a significantly shortened incubation time." (PMID 35979366, 2022). "Reportedly, IL-10 is crucial in the regulation of prion disease." (PMID 35979366, 2022). "Since interleukin-10 and type 1 interferons are key mediators of the antiviral THαβ immunological pathway, protective host immunity against prion diseases may be regulated via THαβ immunity." (PMID 35216001, 2022). "Deficiency of Tgfb1 signaling increases both Aβ accumulation and Aβ-induced neurodegeneration in AD models, and absence of Il10 accelerates prion disease, suggesting neuroprotective roles of Il10-Il10rb signaling." (PMID 31959236, 2020). "Currently no effective treatment strategies exist for prion disease; however, drugs that target the regulation of IL-10, IFN-alpha, or IFN-β, and consequently modulate the THαβ immunological pathway, may prove to be effective therapeutic options." (PMID 35216001, 2022). "Here, IFNAR1 deficiency did not impact upon Il1b mRNA levels and decreased Il10 and Trem2 expression suggesting that canonical IFNAR‐STAT1/2 signaling is dominant in ME7 prion disease." (PMID 30680794, 2019).
rhinitis (10 papers, 2009 to 2024). An inflammation of the mucous membrane lining the nose, usually associated with nasal discharge. "In a murine model of rhinitis, oral administration of B.breve reduced the symptoms and serum specific-IgE, IL-4, IL-10, andincreased CD4+CD25+ T-regulators." (PMID 38687061, 2024). "Results of interest include: total effective rate; total nasal symptom score; rhinitis quality-of-life questionnaire; visual analog scale; laboratory test indicators: IgE, IL6, IL10, or TNF-α levels; recurrence rate; adverse events." (PMID 33761721, 2021). "The outcomes of interest include: total effective rate; the total nasal symptom score; Rhinitis quality of life questionnaire (RQLQ); Visual Analog Scale (VAS); Laboratory inspection indicators: the level of IgE, IL6, IL10 or TNF-α; Recurrence rate; adverse events." (PMID 33546014, 2021).
sarcoma (10 papers, 2013 to 2025). A usually aggressive malignant neoplasm of the soft tissue or bone. "In our CLL cohort, CD5+CD19+CD27+ cells represented the discriminant phenotypic features of IL10+vs- and TGFβ1+vs- subsets, which also resembled CD19+CD81+CD27+CD25+PD-L1hi tumor evoked Bregs producing both IL10 and TGFβ1 in sarcomas." (PMID 36973425, 2023). "The remaining analytes, IL-8, IL-10, IL-12 P40, IL-24, IL-27, and CXCL10 were found in similar plasma concentrations in both patients with sarcoma and healthy subjects." (PMID 41008853, 2025). "In our attempt to check a panel of suppressive molecules in the gene level, it was found more or less downregulation of Arginase 1, iNOS2, STAT3, IL-10, IDO, MMP9 and TGFβ in MDSCs from NLGP-treated surgically sarcoma removed mice." (PMID 28414726, 2017). "In silico analysis confirmed the role of IL-10 in solid tumors including 262 patients affected by sarcoma as a negative prognostic marker for overall survival." (PMID 35328661, 2022).
abdominal aortic aneurysm (9 papers, 2007 to 2025). Enlargement and ballooning of the vessel that supplies arterial blood to the abdomen, pelvis and legs. "The rare IL-10-1082 polymorphism in the promoter region of the IL-10 gene, which is associated with lower levels of the circulating IL-10, is more common in patients with abdominal aortic aneurysm (AAA) and a genetic risk factor for its development." (PMID 33808169, 2021). "Over-expression of IL-10 has also been noted in aortic tissue from abdominal aortic aneurysm (AAA) patients compared to normals or carotid atheroma patients." (PMID 17940614, 2007).
acute liver failure (9 papers, 2006 to 2025). Rapid deterioration of liver function causing encephalopathy and coagulopathy. "Systemic levels of the anti-inflammatory cytokine interleukin 10 (IL-10) are highest in acetaminophen (APAP)-induced acute liver failure (ALF) patients with the poorest prognosis." (PMID 38094302, 2023). "It is well recognized that IL-6 and IL-10 have an important role in improving recovery after acute liver failure." (PMID 28326105, 2017). "Given IL-10’s role in preventing acute liver failure and MCP-1’s importance in activation and recruitment of monocytes, these changes may reflect early hepatic immune dysregulation post-fracture." (PMID 40430063, 2025). "Similarly, several reports show an increased level of cytokines, such as IFN-Ɣ IL-1β, IL-12, IL-4, and IL-10 with ongoing AHE infection and HEV-associated acute liver failure." (PMID 34335528, 2021). "Elevated serum levels of several cytokines, including TNF-α, sTNF-αR1, sTNF-αR2, IL-2, IL-2R, IL-4, IL-6, IL-8, IL-10, and interferon-γ, have been described in patients with ACLF, whereas other studies reported normal TNF-α levels in patients with ACLF or acute liver failure." (PMID 17156425, 2006).